PRKD1 (protein kinase D1)
Diseases named in the same sentence as PRKD1 in open-access papers (continued):
Sharing a sentence is not in itself a finding about the gene and the disease.
prostate carcinoma (23 papers, 2010 to 2025). A carcinoma that arises from epithelial cells of the prostate gland. "We stably transfected LNCaP cells (androgen sensitive prostate cancer cell line with high expression of PrKD1 and AR), with T120-mutated beta-catenin, wild type beta-catenin (WT) or empty vector." (PMID 29108267, 2017). "We have previously shown that down regulation of PrKD1 is associated with prostate cancer progression through several molecular mechanisms including nuclear translocation of beta-catenin and by influencing AR transcriptional activity." (PMID 29108267, 2017). "There is increasing evidence that loss of PrKD1 expression contributes to progression of several human cancers including prostate cancer." (PMID 29108267, 2017). "The PrKD1 promoter activity was measured in LNCaP prostate cancer cells co-transfected with either T120 mutated or wild type beta-catenin (WT) and PrKD1-promoter reporter." (PMID 29108267, 2017). "While the precise initiating mechanism leading to down regulation of PrKD1 in prostate cancer is unclear, the down regulated PrKD1 leads to loss of T120 phosphorylation of beta-catenin, which increases active nuclear beta-catenin with attendant consequences on downstream transcriptional activity." (PMID 29108267, 2017). "Previous studies uncovered the downregulation of PRKD1 expression in cancers such as invasive breast cancer and advanced prostate cancer." (PMID 40984898, 2025). "In view of its critical roles in PCa, PRKD1 inhibition is exploited as a therapy for advanced prostate cancer." (PMID 38201476, 2023). "While PrKD1 is up regulated in pancreatic and skin cancers, it is down regulated in breast, gastrointestinal and advanced prostate cancers." (PMID 29108267, 2017). "The study for the first time identifies a novel auto-repressive loop for PrKD1 expression that perpetuates PrKD1 down regulation contributing to disease progression in prostate cancer." (PMID 29108267, 2017). "The increased active nuclear beta-catenin through interaction with MYC/MAX transcription factor functions as a co-repressor of PrKD1 expression and thereby perpetuates the down regulation of PrKD1 in advanced prostate cancer." (PMID 29108267, 2017). "The interaction creates a novel auto-repressive loop that perpetuates PrKD1 down regulation in prostate cancer." (PMID 29108267, 2017). "We have published a PrKD1 centered signaling biomarker panel that can be used to discriminate aggressive from indolent prostate cancer." (PMID 29108267, 2017). "The down regulation of PrKD1 in advanced prostate cancer increases AR activity through at least two distinct mechanisms." (PMID 29108267, 2017). "The down regulation of PrKD1, among other mechanisms, contributes to increased AR activity and progression of prostate cancer including castration resistance." (PMID 29108267, 2017). "The down regulation of PrKD1 and improved understanding of its role in prostate cancer progression makes PrKD1 an attractive target for therapeutics and biomarker development." (PMID 29108267, 2017). "Because PrKD1 down regulation in advanced prostate cancer contributes to prostate cancer progression and castration resistance by increasing AR transcriptional activity, therapeutic targeting of PrKD1 through transcriptional regulation is a novel possibility." (PMID 29108267, 2017). "While epigenetic inactivation of Prkd1 by hypermethylation of the gene promoter has been described in breast and gastric cancer, repression of Prkd1 expression by nuclear β-catenin has been observed in colon and prostate cancer." (PMID 40461488, 2025). "Although Snail has been shown to regulate motility and invasive capacity as prostate cancer progresses, and protein kinase D1 to suppress EMT through phosphorylation of Snail, the regulatory mechanisms of stability and subcellular localization of Snail in prostate cancer have remained elusive." (PMID 30631151, 2019).
prostate carcinoma (continued). "PRKD1 phosphorylation of β-catenin at Thr112/Thr120 could be critical for cell-cell adhesion in prostate cancer cells." (PMID 26895471, 2016). "It was reported that CUR could activate protein kinase D1 (PKD1) suggesting that suppressing of β-catenin transcriptional activity prevents growth of prostate cancer." (PMID 23970932, 2013). "Moreover, addition of MYC/MAX to PrKD1 centered biomarker panel may improve the performance of the panel in discriminating indolent from aggressive prostate cancer." (PMID 29108267, 2017). "Therefore, we explored alternate mechanisms of PrKD1 regulation in prostate cancer." (PMID 29108267, 2017). "To investigate the effect of beta-catenin on PrKD1 gene regulation, we performed CHIP assays using high PrKD1 expressing LNCaP prostate cancer cell lysate and beta-catenin antibody." (PMID 29108267, 2017). "NCOA1, as the androgen receptor (AR) coactivator, was found to be involved in prostate cancer progression, while NCOA1 knockdown induced a significant decrease in migration and invasion through the upregulation of protein kinase D1 (PRKD1)." (PMID 28060733, 2017). "We propose that in advanced prostate cancer, miR-410 upregulation leads to PRKD1 inhibition that promotes EMT, likely via non-phosphorylation of SNAIL and other mechanisms such as β-catenin activation." (PMID 38201476, 2023). "While additional studies are needed to prove the feasibility and efficacy of targeting in prostate cancer, it is conceivable that targeting the transcriptional regulators such as MYC/MAX could selectively and indirectly increase the PrKD1 expression in cells." (PMID 29108267, 2017). "The treatment of C4-2 prostate cancer cells (more invasive derivative of LNCaP cells and with comparatively lower expression of PrKD1) with MYC inhibitor increased the transcriptional expression of PrKD1 confirming the negative regulatory role of MYC on PrKD1 expression." (PMID 29108267, 2017).
pancreatic cancer (19 papers, 2015 to 2026). "Prkd1-deficiency in pancreatic cancer cells increases α6β4 loading into extracellular vesicles that requires CD82." (PMID 35159011, 2022). "Another study found that loss of protein kinase D1 contributed to metastasis of pancreatic tumors to the lung in mice by increasing the release of EVs, which showed upregulated loading of integrin α6β4." (PMID 35884437, 2022). "The expression of PRKD1 is, however, downregulated in human pancreatic cancer." (PMID 35159011, 2022). "Additionally, PRKD1 has been identified as a suppressor of motility in pancreatic cancer." (PMID 39113699, 2024). "ROS can also promote the pancreatic cancer formation by activating NF-κB and upregulating EGFR proliferative signaling via protein kinase D1." (PMID 37528424, 2023).
cardiac hypertrophy (18 papers, 2012 to 2026). "Protein kinase D1 (PKD1) is a key player in the development of cardiac hypertrophy and has been studied as a potential target to restore cardiac function in the hypertrophied heart." (PMID 41596248, 2026). "For example, as protein kinase D1 (PKD-1) activator, LPA promotes angiogenesis and microvascular remodeling, which are closely associated with cardiac hypertrophy." (PMID 30283359, 2018).
Obesity (11 papers, 2015 to 2026). Accumulation of substantial excess body fat. "In cardiomyocytes, protein kinase D1 overexpression improved insulin resistance, but in contrast, loss in activity preserved cardiac function in obesity." (PMID 38581667, 2024). "Despite this, some obesity-related interactions still have been found, including PRKD1-FTO and WNT4-WNT5A." (PMID 31118946, 2019).
diabetes (8 papers, 2009 to 2024). "Hence, we next investigated if the expression and activities of GSK3β and protein kinase D1 were altered in arteries during diabetes." (PMID 38581667, 2024).
invasive breast carcinoma (8 papers, 2009 to 2025). A carcinoma that infiltrates the breast parenchyma. "PKD1 expression previously has been shown to be downregulated in invasive breast carcinoma through epigenetic silencing of its PRKD1 gene promoter." (PMID 30555634, 2018). "PKD1 (protein kinase D1) encoded by PRKD1 gene is abnormally methylated and silenced in invasive breast cancer cells." (PMID 29298879, 2018). "To start testing this hypothesis, we determined whether the PRKD1 gene can be reexpressed in invasive breast cancer and if this could reverse the invasive phenotype in vitro as well as in vivo (and6)." (PMID 23971832, 2013). "Protein Kinase D1 is downregulated in its expression in invasive ductal carcinoma of the breast and in invasive breast cancer cells, but its functions in normal breast epithelial cells is largely unknown." (PMID 22276203, 2012). "Protein kinase D1 (PRKD1) functions as a key regulator of many cellular processes and is downregulated in invasive breast cancer cells." (PMID 26895471, 2016).
colon cancer (7 papers, 2014 to 2025). "There is paucity of data regarding regulation of PrKD1 gene expression in the published literature other than DNA methylation being involved in PrKD1 down regulation in gastric cancers and by nuclear beta-catenin in colon cancer." (PMID 29108267, 2017). "PKD1 (Protein Kinase D1), a serine-threonine kinase, has been reported to modulate the β-catenin functions in colon cancer." (PMID 28054945, 2017). "Down regulation of Protein Kinase D1 (PrKD1), a novel serine threonine kinase, in prostate, gastric, breast and colon cancers in humans leads to disease progression." (PMID 29108267, 2017). "While the down regulation of PrKD1 by DNA methylation in gastric cancer and by nuclear beta-catenin in colon cancer has been shown, the regulatory mechanisms in other cancers are unknown." (PMID 29108267, 2017). "Herein, for the first time, we demonstrate that a serine-threonine kinase, Protein Kinase D1 (PKD1), modulates the functions of β-catenin to suppress colon cancer growth." (PMID 25149539, 2014).
ectodermal dysplasia (6 papers, 2020 to 2025). "For instance, PRKD1 (protein kinase Db1) has an activating variant at this position: p.Arg603His, seen in telangiectasia-ectodermal dysplasia-brachydactyly-cardiac anomaly syndrome shows constitutive catalytic activity." (PMID 41152984, 2025). "Individuals with a heterozygous mutation in PRKD1 may have facial dysmorphism, ectodermal dysplasia and may have CHDs such as pulmonary stenosis, atrioventricular septal defects, coarctation of the aorta and bicuspid aortic valve." (PMID 38419169, 2024). "Mutations in the PRKD1 gene can lead to congenital heart defects and ectodermal dysplasia." (PMID 37035742, 2023). "Both mutations suggested a dominant gain of function in PRKD1.Thus, an autosomal dominant PRKD1-associated OMIM phenotype termed congenital heart defects, and ectodermal dysplasia was recognized (OMIM: 617364)." (PMID 33919081, 2021).
gastric cancer (6 papers, 2016 to 2025). A primary or metastatic malignant neoplasm involving the stomach. "Epigenetic inactivation of PrKD1 through hypermethylation of the gene promoter has been reported as the mechanism of PrKD1 down regulation in breast and gastric cancer." (PMID 29108267, 2017). "The IMAGiC model predicts response to ICI in patients with advanced gastric cancer based on the expression signature of four genes (ubiquitin C-terminal hydrolase L1 [UCHL1], tyrosine kinase 2 [TYK2], protein kinase D1 [PRKD1], and armadillo repeat-containing X-Linked 1 [ARMCX1])." (PMID 37877810, 2024).
heart failure (6 papers, 2018 to 2025). Inability of the heart to pump blood at an adequate rate to meet tissue metabolic requirements. "Findings from GWAS and Mendelian randomization-proteomics identify seven (CAMK2D, PRKD1, PRKD3, MAPK3, TNFSF12, APOC3 and NAE1) proteins as potential targets for interventions to be used in primary prevention of heart failure." (PMID 37429843, 2023).
bladder cancer (4 papers, 2021 to 2025). "We analyzed PRKD1 expression across bladder cancer (BLCA), kidney chromophobe (KICH), and rectal adenocarcinoma (READ) using data from the Gene Expression Omnibus (GEO) to validate our previous results." (PMID 40984898, 2025).
pancreatitis (4 papers, 2017 to 2025). Inflammation of the pancreas. "Moreover, another study has reported that PRKD1 mediated NFκB signaling was responsible for controlling inflammatory processes in vivo e.g. immune cell infiltration, inflammation and IL6 release, which were abrogated by employing a PRKD inhibitor in a model of experimental pancreatitis in rats." (PMID 36936923, 2023).
breast tumors (3 papers, 2013 to 2018). "Our data suggest that the status of epigenetic regulation of the PRKD1 promoter can provide valid information on the invasiveness of breast tumors and therefore could serve as an early diagnostic marker." (PMID 23971832, 2013). "Most interestingly, high PRKD1 expression is a poor prognostic factor in ER+ tamoxifen-treated breast tumors, suggesting that PKD1 participates to endocrine therapy resistance in the clinics." (PMID 29796183, 2018). "PRKD1 expression is downregulated in invasive human breast tumors as compared with normal breast tissue." (PMID 26895471, 2016). "Taken together, our data suggest a role for PRKD1 promoter silencing by methylation as a measure of how the invasive potential of breast tumors is achieved or increased." (PMID 23971832, 2013). "The poorer prognosis of TNBC expressing high PRKD1 levels suggests that PKD1 plays a role in the biology of TN breast tumors and could represent a therapeutic target for their treatment." (PMID 29796183, 2018). "We utilized this method to specifically determine PRKD1 promoter methylation in breast tumor cells." (PMID 23971832, 2013). "In our cohort, we did observe that PKD1 is down-regulated in primary breast tumors as compared to normal breast tissue (data not shown) and we also showed that high PRKD1 mRNA levels are predictive of a poorer prognosis in both the entire cohort and the TNBC subgroup." (PMID 29796183, 2018). "To determine whether the expression of PKD family members is associated with prognosis in breast cancer, we first analyzed PRKD1, PRKD2 and PRKD3 mRNA levels by quantitative RT-PCR in a large series of 527 primary breast tumors with known clinical/pathological status and long-term outcome." (PMID 29796183, 2018).
head and neck cancer (3 papers, 2013 to 2024). A primary or metastatic malignant neoplasm affecting the head and neck. "These are novel findings, since none of ACE1, FLOT1 and PRKD1 have previously been investigated in laryngeal or head and neck cancer, neither is it known whether these genes are functional in the normal laryngeal epithelium." (PMID 23950933, 2013).
salivary gland neoplasm (3 papers, 2018 to 2025). Tumors of the SALIVARY GLANDS. "In this article, we describe a unique case of CASG arising in the sinonasal cavity of a 49-year-old female, with a novel NAP1L1::PRKD1 fusion, expanding the molecular complexities of salivary gland neoplasms." (PMID 41357817, 2025). "The detection of a PRKD1 p.Glu710Asp hotspot mutation or the translocation of one of the PRKD1, PRKD2, or PRKD3 genes is now considered highly specific for the diagnosis of PAC, as these molecular alterations are rarely detected in other salivary gland tumours." (PMID 38201647, 2024).
hypertrophic cardiomyopathy (2 papers, 2020 to 2023). A condition in which the myocardium is hypertrophied without an obvious cause. "The main aim of the present study was to investigate the effects of PKD on titin phosphorylation in vivo and resulting functional changes using cardiomyocyte specific Prkd1, which encodes for PKD1, knockout mice, SILAC mouse hearts, and human hypertrophic cardiomyopathy (HCM) heart tissues." (PMID 32351396, 2020).
ischemic stroke (2 papers, 2017 to 2025). A stroke disorder caused by obstruction of blood flow to the brain, due to thrombotic (local blood clot formation) or embolic (due to a blood clot or other material traveling from another site) event. "The serine/threonine protein kinase D1 (PKD1) confers neuroprotection in various neuropathological conditions, including ischemic stroke." (PMID 40461488, 2025).
melanoma (2 papers, 2022 to 2026). A malignant, usually aggressive tumor composed of atypical, neoplastic melanocytes. "Our multi-omics analysis revealed PRKD1, JUN, and NCK1 as key resistance nodes, offering potential targets for therapeutic strategies to counter resistance in melanoma." (PMID 41708984, 2026).
metastatic prostate carcinoma (2 papers, 2017 to 2023). A carcinoma that arises from the prostate gland and has spread to other anatomic sites. "PRKD1 belongs to the family of calcium calmodulin kinases, which has been reported to be reduced in metastatic prostate cancer as compared to the localized disease." (PMID 38201476, 2023). "Data sets with significant down regulation of PrKD1 in metastatic prostate cancer were identified, and the gene expression data for MYC, MAX and MXD1 were compared." (PMID 29108267, 2017).
pancreatic ductal adenocarcinoma (2 papers, 2016 to 2023). An infiltrating adenocarcinoma that arises from the epithelial cells of the pancreas. "Increased expression of PRKD1 and its gene product protein kinase D1 (PKD1) are linked to oncogenic signaling in pancreatic ductal adenocarcinoma, but a direct functional relationship to oncogenic KRas has not been established so far." (PMID 27649783, 2016).
skin cancer (2 papers, 2017 to 2025). "A total of seven genes were obtained; of these, PRKD1, also known as serine/threonine‐protein kinase D1, is reported to play a crucial role in promoting acinar‐to‐ductal metaplasia, wound healing, and skin tumor formation closely related to cancer progression." (PMID 40126353, 2025).
Adult onset (1 paper, 2017). Onset of disease manifestations in adulthood, defined here as at the age of 16 years or later. "Interestingly, in a similar manner, we found negative associations between genetic variants of PRKD1 and adult-onset asthma (decreased risk) and positive associations between genetic variants near RELA and adult-onset asthma (increased risk) in participants exposed to LMW or irritant agents." (PMID 27504716, 2017).
asthma (1 paper, 2017). "This study identified interactions between genetic variants near or within five genes, PLA2G4A, PLA2R1, RELA, PRKD1 and PRKCA, and occupational exposures to LMW agents or irritants for current adult-onset asthma." (PMID 27504716, 2017). "Overall, all these data suggest that any or all of these genes—PLA2G4A, PLA2R1, RELA, PRKD1, and PRKCA—may play a role in the risk of asthma in adults in association with exposure to LMW agents or irritants." (PMID 27504716, 2017).
atrioventricular septal defects (1 paper, 2024). "We show that homozygous deletion of Prkd1 is associated with complex forms of CHD such as atrioventricular septal defects, and bicuspid aortic and pulmonary valves, and is lethal." (PMID 38419169, 2024).
autism (1 paper, 2023). Persistent deficits in social interaction and communication and interaction as well as a markedly restricted repertoire of activity and interest as well as repetitive patterns of behavior. "Case-control studies have shown that de novo mutations in the PRKD1 gene occur more frequently in patients with autism than in the general population." (PMID 37035742, 2023).
autoimmune disease (1 paper, 2021). A disorder resulting from loss of function or tissue destruction of an organ or multiple organs, arising from humoral or cellular immune responses of the individual to their own tissue constituents. "PRKD1 variants were reported in three families with mixed autoimmune disease including SS." (PMID 34400910, 2021).